ZEB1 (zinc finger E-box binding homeobox 1)
Diseases named in the same sentence as ZEB1 in open-access papers (continued):
Sharing a sentence is not in itself a finding about the gene and the disease.
colon carcinoma (continued). "In the pathogenesis of metastatic CRC, abundant miR-200c could be detected in liver metastasis tissues, and overexpression of miR-200c in colon cancer cell lines led to a reduced expression of its target genes ZEB1, ETS1 and FLT1, and EMT markers (E-cadherin and vimentin)." (PMID 26064956, 2015). "This indicates that IL-1β may act through Zeb1 to induce EMT in colon cancer cells." (PMID 23174018, 2012). "Thus, the parallel up-regulation of Zeb1 and Bmi1 by IL-1β suggests that IL-β-induced self-renewal of colon cancer cells may involve the Zeb1-Bmi1 pathway." (PMID 23174018, 2012). "At least in colon cancer, ALDH1A3 increases invasion by upregulating EMT-inducing transcription factor zinc finger E-box binding homeobox 1 (ZEB1) and SNAI2 and by inhibiting MET-promoting miR-200 family microRNAs." (PMID 39251846, 2024). "Comparisons between the high and low tissue expression of VIP and ZEB1 were performed based on the GSA results, focusing on the EMT and cell cycle pathways in gastric and colon cancer." (PMID 37444395, 2023). "Therefore, IL-1β and Zeb1 could be potential therapeutic targets for colon cancer treatment." (PMID 37176567, 2023). "In colon cancer, NUCB-2/nesfatin-1 enhanced migration, invasion and EMT through LKB1/AMPK/TORC1/ZEB1 pathways in vitro and in vivo." (PMID 37635259, 2023). "In colon cancer, ALDH1A3 upregulated transcription factor zinc finger E-box binding homeobox 1 (ZEB1) and snail family transcriptional repressor 2 (SNAI2) by inhibiting miR-200 family members, leading to increased invasion." (PMID 36672441, 2023). "Studies suggest that IL-1β promotes colon tumor growth by activating cancer stem cell (CSC) self-renewal and epithelial-to-mesenchymal transition (EMT) through the transcription factor Zinc Finger E-box binding homeobox 1 (Zeb1)." (PMID 37176567, 2023). "In a recent study, we demonstrated that knocking down TRPV4 in colon cancer cells suppressed their malignant potential by activating PTEN, and decreased their invasiveness via inhibition of ZEB1 signaling." (PMID 36619170, 2022). "Co-culture with Schwann cells increased the expression of mesenchymal markers, such as ZEB1, Vimentin, and N-cadherin, and attenuated the expression of epithelial markers, such as E-cadherin and ZO1 in colon cancer cells." (PMID 36522730, 2022). "In colon cancer, lncRNA H19 competitively combined with miR-138 and miR-200a, up-regulating the expression of key genes in EMT (VIM, ZEB1, and ZEB2), and promoting the progress of EMT." (PMID 35094653, 2022). "ZEB1 and ESRP1 differential expression in quasi-mesenchymal and highly metastatic EpCAMlo colon cancer cells." (PMID 36346211, 2022). "Similar to these reports, the present study found that circCSPP1 promoted the progression of colon cancer by sponging a new microRNA miR-431 and regulating the expression of ROCK1 and ZEB1." (PMID 35101080, 2022). "In summary, this study provides evidence that GOLPH3 is involved in regulating colon cancer cell invasion and migration through the STAT3 pathway and silencing GOLPH3 down-regulates ZEB1 and Integrin α3 expression to prevent CRC metastasis." (PMID 35372504, 2022). "Increasing studies have demonstrated that TGF-β accelerates the metastasis of colon cancer by upregulating the expression of EMT-promoting genes, such as Snail and ZEB1." (PMID 35135542, 2022). "Consistent with the present findings, we previously reported that knocking down TRPV4 suppressed colon cancer cell growth via PTEN activation, and inhibited invasiveness by blocking ZEB1 signaling." (PMID 36619170, 2022). "PTK6 knockdown resulted in a decrease in E-cadherin and ZO-1 epithelial markers and an increase in vimentin, ZEB1, and claudin-1 mesenchymal markers via STAT3-MEK5/ERK5 in colon cancer cells, which was reversed by PTK6 reintroduction." (PMID 33572742, 2021).
colon carcinoma (continued). "Colon cancer cells were transfected with siRNA against TRPV4 or HC067047 (a selective TRPV4 antagonist), TRPV4 full-length plasmid or siRNA against ZEB1, or both, in order to measure cell migration and invasion." (PMID 34814869, 2021). "For instance, it inhibits colon cancer by inhibiting TUSC3/AKT signal transduction and inhibits rectal cancer progression via targeting ZEB1 to regulate epithelial-mesenchymal transition." (PMID 33102581, 2020). "To validate the effect of miR-200a on the abrogation of ZEB1 by AXT, we generated miR-200a knockdowned colon cancer cells by transfecting miR-200a sponge." (PMID 31263239, 2019). "In this study by using publicly available microarray datasets, we for the first time showed a negative correlation between EVI1 and all the known EMT related transcription factors (SNAIL, SLUG, ZEB1, ZEB2, TWIST1, and TWIST2) in colon cancer patient samples." (PMID 29339729, 2018). "In these terms, inhibition of ZEB1 and subsequent upregulation of CDH1 becomes an advantageous strategy especially in the case of patients with advanced stages of colon cancer." (PMID 29352232, 2018). "Genistein reversed the EMT of colon cancer cells by upregulation of E-cadherin and downregulation of N-cadherin, accompanied by the suppression of EMT related makers, such as Snail2/slug, ZEB1, ZEB2, FOXC1, FOXC2 and TWIST1." (PMID 29202800, 2017). "Thus, ZEB1 could regulate colon cancer invasiveness by inducing EMT and MMP production." (PMID 28811578, 2017). "Similar to our results, it has been reported that stimulation with IL-6 will up-regulate the expression of ZEB1 and down-regulate ZO1 expression in colon cancer cells." (PMID 29383101, 2017). "DDB2 has been described as down-regulated in high-grade colon cancers moreover, it plays a dominant role as repressor of EMT genes (VEGF, Zeb1 and Snail) in colon cancer cells." (PMID 28061476, 2017). "It indicates the NUCB-2/AMPK/TORC1 pathways are upstream pathways of ZEB1 and EMT properties in colon cancer." (PMID 27150059, 2016). "In another study for colon cancer, the author reported that expression of VDR was negatively correlated with those of snail and ZEB1 in the cancer tissue." (PMID 27548154, 2016). "Markers that indicate EMT in tissues are sparse, and detection of typical EMT markers such as ZEB1, SNAIL1, or Vimentin is difficult in primary colon cancers, as reflected by few convincing in situ studies." (PMID 27120783, 2016). "Other studies showed absence of correlation or a significant direct correlation between ZEB1 and VDR RNA expression in colon cancer." (PMID 26880977, 2016). "Here, we provide direct evidence that IL-1β promotes self-renewal of colon cancer cells as well as their acquisition of EMT phenotype, and this induction of CSC and EMT phenotypes was mediated by Zeb1." (PMID 23174018, 2012). "Thus, IL-1β and Zeb1 might be new therapeutic targets against colon cancer stem cells." (PMID 23174018, 2012). "Whereas overexpression of CDK5RAP2 S down-regulated E-cadherin and up-regulated N-cadherin, Vimentin, Zeb1, Slug and Twist1 expression, indicating that CDK5RAP2 L and CDK5RAP2 S might have different roles in EMT of colon cancer cells." (PMID 39048555, 2024). "Taken together, the findings of the present study indicated that circCSPP1 may function as a competing endogenous RNA in the progression of colon cancer by regulating the miR-431/ROCK1 and miR-431/ZEB1 signaling axes." (PMID 35101080, 2022). "Accordingly, among the top differentially expressed genes (DEGs) between EpCAMlo and EpCAMhi in SW480 and HCT116 colon cancer cells, ESRP1 was found to be downregulated both at the RNA and at the protein level in the quasi-mesenchymal subpopulation where ZEB1 expression is upregulated." (PMID 36346211, 2022).
colon carcinoma (continued). "Accordingly, ZEB1 upregulation in EpCAMlo colon cancer cells is invariably accompanied by ESRP1/2 downregulation, and ZEB1hi/ESRP1lo colon cancers, predominantly belonging to the mesenchymal CMS4 subgroup, have a significantly worse survival outcome when compared with ZEB1lo/ESRP1hi patients." (PMID 36346211, 2022). "To determine whether the ZEB1 and integrin α3 is regulated by STAT3 signaling in colon cancer cells, we used two independent siRNAs to knock down STAT3’s expression and then examined the expression of ZEB1, integrin α3 and GOLPH3 in HCT116 and HCT8 cells." (PMID 35372504, 2022). "In addition, circCSPP1 promoted the progression of colon cancer functions as a competing endogenous RNA by the regulating miR-431/ROCK1 and miR-431/ZEB1 pathways." (PMID 35101080, 2022). "Additionally, miR-200a, belonging to the miR-200 family, inhibits colon cancer EMT by targeting and repressing ZEB1/2." (PMID 31744051, 2019). "ZEB1 mRNA and protein expression were dramatically suppressed in AXT-treated colon cancer cells." (PMID 31263239, 2019). "Moreover, individual markers that indicate or drive EMT in colon cancer showed a significant overexpression in tumors with high RBP7 expression, including ZEB1 (r = 0.27, P < 0.0001) and ZEB2 (r = 0.36, P < 0.0001)." (PMID 31598160, 2019). "Similarly, differential expression of some transcription factors involved in epithelial-to-mesenchymal transitions (i.e. ZEB1, SNAI1, and SNAI2) was variably observed in the colon cancer cell lines when exposed to the inflammatory media." (PMID 29462209, 2018). "We found that the expression of ZEB1, SNAI1 and SNAI2 were clearly induced in the two colon cancer cell lines by MACRO-CM from U937 macrophages, with the exception of HT-29 cells that did not expressed detectable levels of SNAI2 mRNA under any culture condition." (PMID 29462209, 2018). "Transfection of miR-205-5p in colon cancer cells induced low levels of ZEB1, a direct target of the non-coding sequence, results that overlap with data from previous studies." (PMID 29352232, 2018). "ZEB1 promotes migration and invasion by inducing EMT in colon cancer." (PMID 28088787, 2017). "Moreover, markers that induce or indicate EMT in colon cancer were significantly overexpressed in tumors with high CYB5R1 levels, including ZEB1 (r=0.20, p<0.0001), TWIST1 (r=0.22, p<0.0001), and VIM (r=0.29, p<0.0001)." (PMID 27120783, 2016). "Here, we show that silencing or removing H2A.X, a histone H2A variant involved in cellular DNA repair and robust growth, induces mesenchymal-like characteristics including activation of EMT transcription factors, Slug and ZEB1, in HCT116 human colon cancer cells." (PMID 26876487, 2016). "Using a colon cancer cell line and primary colon cancer cells, we have demonstrated that IL-1β may act via Zeb1 to promote EMT and stem cell development in colon cancer cells, which may contribute to colon tumor malignancy." (PMID 23174018, 2012). "Our findings indicate that IL-1β may promote colon tumor growth and invasion through activation of CSC self-renewal and EMT, and Zeb1 plays a critical role in these two processes." (PMID 23174018, 2012). "CLDN-1 might enhance Zeb-1 levels through phosphatidylinositol-3 kinase (PI3K)/protein kinase B (Akt) pathway and Wnt/β-catenin pathway to suppress E-cadherin-related EMT pathogenesis in colon cancer." (PMID 33407452, 2021). "In addition, Xihuang pill regulates the expression of E and N cadherin through regulation of the ERK pathway and ZEB1-SCRIB cycle and represses the epithelial-mesenchymal transition of human colon cancer cells, thus inhibiting the invasion and metastasis of tumor cells." (PMID 28458715, 2017). "Furthermore, transfecting colon cancer cells with Wnt5a led to downregulation of transcription factors considered key regulators of EMT, such as Twist and Zinc finger E-box-binding homeobox 1 (ZEB1), and induction of an epithelial phenotype by enhancing the expression of E-cadherin." (PMID 27571105, 2016).
colon carcinoma (continued). "Since Zeb1, a transcription factor that mediates EMT, was up-regulated in IL-1β-induced stem cells in serum free medium, we then investigated whether IL-1β could induce EMT phenotype in colon cancer cells." (PMID 23174018, 2012). "Similarly, the evidence of ZEB1/GSDME involvement in the regulation of EMT markers upon ETAR activation in breast and colon cancer, suggested that this novel EMT-related nuclear function of GSDME may be common to various tumor histotypes, in addition to HG-SOC." (PMID 41545335, 2026). "Interestingly, ZEB1 has been shown to be a downstream target of TAZ in retinal pigment epithelial cells, suggesting that ZEB1 may act as a downstream effector of TAZ to promote cancer metastasis, while ZEB1 and ZEB2 have also been shown to be prognostic markers in colon cancer." (PMID 23372686, 2013). "When Zeb1 expression was normalized to that of Fbxo45, but not Siah1, the DFS of colon cancer patients with higher Zeb1/Siah1 levels was statistically significantly reduced compared to patients with lower values." (PMID 30979372, 2019).
glioma (104 papers, 2013 to 2026). A benign or malignant brain and spinal cord tumor that arises from glial cells (astrocytes, oligodendrocytes, ependymal cells). "For gliomas, in contrast, new research has shown that ZEB1 loss increases glioma stem cell tumorigenicity and resistance to chemoradiation, and ZEB1 deletion is associated with shorter patient survival." (PMID 41226394, 2025). "The loss of ZEB1 increases stemness of gliomas and this mutation presumably occurred at the stem cell level." (PMID 30705664, 2018). "Micro-RNAs such as mIR-200 and miR-141 were also shown to inhibit ZEB1 resulting in decreased glioma growth suggesting that ZEB1 expression is the resulting cause of glioma progression." (PMID 30705664, 2018). "Our research studied the role of ZEB1 loss on patient survival in gliomas and in maintaining glioma cancer stem cell (GSC) properties." (PMID 32309604, 2018). "Given that ZEB1 loss occurs on 10p, it is likely that the occurrence of ZEB1 loss in lower grade gliomas and 10q loss in secondary glioblastomas occur independently." (PMID 28246407, 2017). "We studied the role of ZEB1 loss in maintaining glioma cancer stem cell properties and its impact on patient survival in gliomas." (PMID 28246407, 2017). "Given the copy number loss and increased number of mutations now identified for ZEB1, we sought to determine if there was a relationship between ZEB1 expression and survival in either lower grade glioma or GBM." (PMID 28246407, 2017). "Taken together these data suggest that ZEB1 loss is an important prognostic indicator and is associated with unfavorable outcome for both lower grade gliomas and GBM patients." (PMID 28246407, 2017). "Meta-analysis of ZEB1 copy number status in 2,988 cases of glioma revealed disruptive ZEB1 deletions associated with decreased survival." (PMID 28246407, 2017). "Although it is unclear the impact of the identified ZEB1 mutations, the degree to which ZEB1 mutations occur suggests that these mutations contribute to ZEB1 loss in both lower grade gliomas and GBMs." (PMID 28246407, 2017). "ZEB1 is associated with invasive glioma cells, with an increase in ZEB1-immunoreactive cell numbers in higher-grade tumours." (PMID 23818228, 2013). "ZEB2 has previously been confirmed to be associated with the malignant phenotype of glioma, and the expression level of ZEB1 was significantly increased in glioma tissues compared to normal brain tissues, being positively correlated with WHO glioma classification." (PMID 40679044, 2025). "ZEB1 increases loss of cell–cell contact and therefore fosters increased motility in glioma." (PMID 31429770, 2019). "Importantly, copy number loss of ZEB1 correlated with shortened patient survival in both lower grade gliomas (***P < 0.0001) and GBMs (**P = 0.002, e respectively)." (PMID 28246407, 2017). "Moreover, a direct interaction between Olig2 and ZEB1 seems to exist and cause reciprocal stimulation, reinforcing the invasion capacity of glioma cells." (PMID 29261132, 2017). "Thus, expression of ZEB1 seems to be associated with infiltrating tumour cells across a spectrum of glioma." (PMID 23818228, 2013). "Knocking out ZEB1 in GBM cells inhibits the expression of key glioma stem cell markers, including CD133, SOX2, and OLIG2, thereby suppressing GSC initiation, invasion, and chemoresistance." (PMID 41141394, 2026). "This, along with Notch-mediated overexpression of SNAIL, ZEB1, and vimentin, further enhances glioma cell invasion and migration." (PMID 41141394, 2026). "The LINC00645 is induced by TGF-β and plays a key role in TGF-β-induced mesenchymal differentiation by sponging miR-205-3p, which in turn targets ZEB1, thus promoting ZEB1 expression as well as TGF-β-induced glioma cell invasion and migration." (PMID 38256140, 2024). "This in turn binds the tyrosine kinase receptor A (TrKA) and integrin-β1 on GSCs, triggering NF-kB and zinc finger E-box binding homeobox 1 (ZEB1) activation which promote glioma cell infiltration." (PMID 38473812, 2024).